CDK4 (cyclin dependent kinase 4)
Diseases named in the same sentence as CDK4 in open-access papers (continued):
Sharing a sentence is not in itself a finding about the gene and the disease.
tumor (continued). "In addition to these well-known tumor suppressors, some circRNAs could also regulate tumor growth by regulating cell cycle mediators, such as Cyclin D1, a well-known regulator of the cell cycle that promotes the transition from G1 to S phase by activating CDK4 or CDK6." (PMID 30999909, 2019). "We found that the expression of cyclin D1 and CDK4 was significantly elevated in GC tissues versus adjacent non‐tumour tissues." (PMID 30714150, 2019). "In addition, LP6 cells showed a much more aggressive tumor formation in vivo than the 5H-MDM2 and CDK4 cells, despite their low growth potency in vitro." (PMID 31160689, 2019). "On immunohistochemical staining, the tumor cells were found to be diffusely positive for α-smooth muscle actin (α-SMA), desmin, and caldesmon and negative for CD34, S100, c-kit, MDM2, and cyclin-dependent kinase 4 (CDK4)." (PMID 31342204, 2019). "On the other hand, the RB1 loss-of-function signature (designed to predict the absence of benefit to CDK4/6 inhibitors) was also a key characteristic of AFP-high tumours." (PMID 31285588, 2019). "In comparison, nonuterine tumour samples (n=113) were positive for CDK4, CDK6, and p-Rb in 54.9%, 86.7%, and 49.6%, respectively, and expressed ≤10% p16 protein in 41.6%." (PMID 30804704, 2019). "Additionally, this anti-tumor activity of elacestrant translates in vivo in multiple PDX models representing innate and acquired CDK4/6i resistance." (PMID 31852484, 2019). "Previously, triple negative breast cancers were not thought to be a good candidate for treatment with CDK4/6 inhibitors due to approximately 20% of these tumours lacking functional Retinoblastoma-like protein (Rb)." (PMID 31769425, 2019). "When we analysed the site of tumor cell injection by immune-histochemical stainings 21 days after injection we found residual tumor cells that displayed no signs of proliferation upon stable shRNA knockdown for CDK4 and CDK6 when compared to controls." (PMID 30858922, 2019). "In view of the important role of cell cycle arrest in tumor cell growth inhibition, the expression of several cell cycle-related proteins was investigated and RC influences the expression of CDK2 and CDK4, which suggests the feasibility of cell cycle arrest in G0/G1 and G2/M." (PMID 31817918, 2019). "Irrespective of the shRNA mediated knockdown of CDK4 or CDK6 we failed to observe differences in the initial reaction to tumor cell injection; subcutaneous tumor nodules were readily visible." (PMID 30858922, 2019). "Therefore, treatment by the small molecule CDK4/6 inhibitor lowers SPOP and promotes PD-L1 protein expression, priming tumor cells for ICI treatment." (PMID 30863749, 2019). "Furthermore, the authors demonstrated that a combination of endocrine therapy, CDK4/6 inhibition, and PI3K inhibition is even more effective in vitro as well as in PDX models, in which disease stabilization and tumor regression were observed." (PMID 30959874, 2019). "Furthermore, they confirmed this data using PIK3CA mutation-bearing mouse xenografts, in which co-treatment with CDK4/6 and PI3K inhibitors elicited tumor regression." (PMID 30959874, 2019). "Although both CK2 and CDK4 inhibitors have shown promising results against these tumor types, none of these agents have achieved objective responses in the clinic as monotherapies." (PMID 30701029, 2018). "Furthermore, the patient’s tumor harbored amplifications of BRAF, EGFR, MET, and CDK6, which provides a rationale for this tumor’s acquired resistance to the triple BRAF/MEK/CDK4&6 inhibitor treatment applied before sequencing." (PMID 30373609, 2018). "While bioinformatics prediction suggests no epigenetic regulation of let-7 family on CDK4, other mechanisms or pathways of niclosamide exerting its inhibition of tumor cell cycle probably exist." (PMID 30687101, 2018).
tumor (continued). "Alterations to cyclin D1, CDK1, CDK2, CDK4 and p16, which regulate the cell cycle, led us to speculate whether ABHD11‐AS1 affects tumour progression by regulating the protein expression of factors linked to the cell cycle." (PMID 29799152, 2018). "RB1, which is regulated by CDK4, showed a significantly lower expression in CDKN2Ahigh (p < 0.001) and the downstream transcription factor gene E2F3 was significantly higher expressed in CDKN2Ahigh tumours (p < 0.001)." (PMID 30258198, 2018). "After tumours were established (having grown to ∼100–150 mm3), mice were initiated on treatment with vehicle, erlotinib, trametinib, palbociclib or the combination of erlotinib with the MEK or CDK4/6 inhibitor." (PMID 28059068, 2017). "CDK4/6 inhibitors resensitize PDX tumors to HER2-targeted therapies and delay tumor recurrence." (PMID 28499452, 2017). "The Western blot analyses of 2HF treated tumor tissue lysates, as compared with untreated controls, revealed a decrease in the level of proliferation proteins pAKT, survivin, RLIP76, pERK, pJAK2, STAT3, CDK4 and cyclin B1." (PMID 29088842, 2017). "For this reason, because high‐performance phosphospecific CDK4 antibodies are yet to be developed, and because CDK4 is expressed at low level, the immunological detection of CDK4 phosphorylation will be hardly adapted to FFPE tumor samples." (PMID 28566333, 2017). "Altogether, above results suggest that loss of epidermal Rxrα when combined with oncogenic NRAS and activated CDK4 results in melanomagenesis, which is further accelerated by a single neonatal UVB exposure reducing the tumor latency as shown in the Kaplan Meier curve." (PMID 29121869, 2017). "This is in agreement with previous reports that proliferative cues such as cycD and cdk4 do not account for presence of tumour cells in the VNC." (PMID 28346426, 2017). "To determine whether the CDK4 mutant R24A also would inhibit HCC growth in vivo, we conducted xenograft tumor studies." (PMID 27708221, 2016). "Given CDK4/6 inhibitor has been reported to have an anti-angiogenic activity, we performed immunohistochemistry analysis to detect the protein levels of CD31 in the tumor xenograft." (PMID 26909611, 2016). "Interestingly, dinaciclib, an inhibitor against CDK1, 2, 5, and 9 (IC50 1-4nM), but with less activity against CDK4, 6, and 7 (IC50 60-100nM), showed encouraging anti-tumor effect in preclinical studies of TNBC with potential selectivity for MYC driven tumors." (PMID 27486754, 2016). "Furthermore, the CDK4 mutant R24A weakly binds to PRMT5, inhibiting HCC cell cycle progression and tumor growth." (PMID 27708221, 2016). "Various experiments revealed that paboxilin inhibited cell growth or mice tumor proliferation with CDKN2A deletion selectively and sensitively, which indicated that CDKN2A/B CNL may respond to CDK4/6 inhibitor." (PMID 27974690, 2016). "Our findings of CCND1 and/or CDK4 allow us the suggestion that the selective CDK4/6 inhibitor Palbociclib (IBRANCE®, Pfizer Inc.)may be a promising treatment option in unresectable or metastasized tumor stages." (PMID 26943575, 2016). "hSulf-1 exerts its anti-tumor effects by inhibiting cell surface HSPG sulfation, thus lowering downstream AKT signaling pathway activity and decreasing the nuclear import of the cell cycle regulator CDK4." (PMID 27806323, 2016).
tumor (continued). "It is well known that accelerated tumor cell proliferation could occur as a result of CDKN2A/B deletion due to the direct removal of tumor suppressors and activation of tumor growth factors such as MDM2 and CDK4/6." (PMID 27090891, 2016). "Our finding on the repression of SIRT6 transcription by E2F1 will broaden the therapeutic opportunities to enhance SIRT6 tumor suppressor activities with compounds like CDK4/6 inhibitor, which retains E2F1 in the RB-E2F1 complex by diminishing the phosphorylation of RB by CDK4/6." (PMID 25816777, 2015). "In these same cell lines, crystal violet staining after 7 days of treatment demonstrated variable inhibition of tumor cell growth amongst the PDA established lines, with the PANC1 line appearing relatively sensitive to CDK4/6 inhibition and the MIA-PACA2 line appearing relatively resistant." (PMID 26158861, 2015). "The cell cycle regulating proteins cdk1, cdk2 (not in KTC-26), cdk4 (not in A498), cyclin A and cyclin B were all down-regulated in the tumour cells when treated for 24 hrs with sunitinib." (PMID 25444514, 2015). "In conclusion, a relatively non-toxic compound BPT with dual Cdk4/ tubulin polymerization inhibition activity and promising efficacy in in vivo tumour models has been identified." (PMID 25950473, 2015). "The tumor stained negatively for desmin, S-100, c-Kit, CK-AE1/AE3, CDK4 and MDM2." (PMID 26337721, 2015). "In the primary tumor, the copy number of MDM2 was 17.2 whereas the copy number of CDK4 was 2.2." (PMID 25176350, 2014). "A modulation of PD biomarkers in terms of downregulation of EGFR, AKT and CDK4 client proteins was achieved either in vitro, on A431 tumor cells treated with SST0116CL1, and in terms of down-modulation of c-Met, AKT and CDK4 ex vivo in tumor lesions collected from GTL-16 tumor-bearing mice." (PMID 25096516, 2014). "Meanwhile, among the target genes for miR-195 and miR-497 identified in the present study, top four target genes, CCNE1, CDC25A, CDK4 and CDK6, frequently upregulated in a tumor-specific manner only showed slight inverse correlation with these miRNAs in HCC tumors." (PMID 23544130, 2013). "There was, however, a tendency for CDK4 expression to correlate with a high tumor grade (P = 0.156), but not with any of the survival functions (data not shown)." (PMID 23336272, 2013). "Moreover, target genes frequently upregulated in HCC in a tumor-specific manner, such as CDK6, CCNE1, CDC25A and CDK4, showed an inverse correlation in the expression of miR-195 and miR-497, and their targets." (PMID 23544130, 2013). "Overexpression of this gene in the GBM tumor but not the normal brain, therefore, cannot be explained by the tumor's frequent amplification of the CDK4 locus alone." (PMID 24282503, 2013). "In addition, involvement of furin in repression of tumor growth was also supported by decreased expression of cell proliferation related molecules (IR, cyclin D1, CDK2, and CDK4...etc)." (PMID 22808247, 2012). "HSP-90 promotes survival of tumor cell, induces their growth and metastasis even when there are no growth factors via continued protein translation and cellular proliferation; Its client proteins include: KIT, AKT, CDK4, telomerase, Bcl-2, MMP2 and others." (PMID 23164412, 2012).
tumor (continued). "On the other hand, we have not observed differences in cyclin E, CDK2 and CDK4 levels between catalase-treated and non-treated cells and between non-tumor and tumor cells." (PMID 22970236, 2012). "Recent studies suggest that interphase CDKs (CDK4, CDK2) are only essential for proliferation of tumor cells and selective CDK inhibition may provide therapeutic benefit." (PMID 21834972, 2011). "Ectopic PRDM5 expression significantly inhibited tumor cell clonogenicity, accompanied by the inhibition of TCF/β-catenin-dependent transcription and downregulation of CDK4, TWIST1 and MDM2 oncogenes, while knocking down of PRDM5 expression lead to increased cell proliferation." (PMID 22087297, 2011). "Our data showed that although expression of cdk-4, cdk-6, and p27 was not affected by sorafenib, the levels of cyclin D1, cyclin cdk-2, and cyclin B1 in sorafenib-treated tumours were significantly reduced as compared with controls (P<0.05)." (PMID 21407223, 2011). "CDKN2B's neighbor, cyclin-dependent kinase inhibitor 2A (CDKN2A), functions similarly to inhibit Cdk4 and is a known tumor suppressor, but is not detectably expressed in either normal or tumor tissue." (PMID 20174472, 2010). "Additionally, a recent study has indicated that tumorigenesis can be effectively managed by targeting the CDK7-mediated CDK4/RB pathway and that FERM domain-containing 8 disrupts the interaction of CDK7 with CDK4, thereby inhibiting the activation of CDK4 to affect tumor growth." (PMID 40486867, 2025). "Basic research has demonstrated that in tumor mouse models, whether CDK4/6-dependent or independent, trilaciclib does not interfere with the antitumor activity of chemotherapy." (PMID 40277746, 2025). "However, an insufficient therapy response in the presence of CDK4/6i or tumor progression and relapse is not uncommon." (PMID 40452017, 2025). "To explore possible benefits of sequential therapies, we used syngeneic subcutaneous and orthotopic HNSCC tumor model mice to test whether brief CDK4/6i pretreatment could improve subsequent response to anti‐PD‐1, with or without continued CDK4/6i dosing." (PMID 40936164, 2025). "Additionally, alterations in downstream signaling pathways, including PI3K/AKT/mTOR and cyclin D1/CDK4/6, can promote tumor growth independent of estrogen signaling." (PMID 40566067, 2025). "The results reveal that CDK4 and CDK6—cyclin-dependent kinases that promote cell cycle progression—are significantly overexpressed in GBM brain samples, underscoring their role in tumor proliferation and identifying them as critical targets for miR-124 intervention." (PMID 40134003, 2025). "Notably, plasma cell tumor infiltration has not been reported with the CDK4/6-MEK drug combination or the single agents in any tumor model, including MPNST." (PMID 39857943, 2025). "Although previous studies have indicated that CDK4/6 inhibitors suppress Tregs, this effect was not clearly observed in our study, likely due to the opposing influence of RT, which has been reported to increase Treg numbers and recruit them to the tumor site." (PMID 40836337, 2025). "Additionally, the relative and absolute expression levels of CDK4 and CDK6, along with factors within the tumor microenvironment, may offer further insights into treatment responsiveness." (PMID 40282469, 2025). "Moreover, the combination of palbociclib and binimetinib (targeting CDK4/6 and MEK, respectively) was shown to induce tumor cell senescence and matrix remodeling leading to enhanced drug delivery and T-cell infiltration, supporting further study of the combination." (PMID 40928353, 2025).
tumor (continued). "Overall, while CDK4/6 inhibitors offer selective targeting with manageable toxicity, Dinaciclib’s broader inhibition spectrum provides more robust anti-cancer effects, particularly in OSCC, in which multiple CDK-related pathways contribute to tumor progression." (PMID 40076816, 2025). "Additionally, Rb-independent effects of CDK4/6 inhibitors—such as blocking phosphorylation of FOXM1 and FOXO3—further compromise DNA repair capacity post-chemotherapy or radiotherapy across diverse tumor types." (PMID 40421216, 2025). "In addition, CDK4 indirectly supports metabolic adaptation by modulating the activity of enzymes involved in lipid synthesis and nucleotide biosynthesis, pathways that are frequently co-opted by MYC to support tumor growth." (PMID 40076599, 2025). "Selective inhibitors of various kinases, including cyclin-dependent kinases 4 and 6 (CDK4/6), epidermal growth factor receptor (EGFR) tyrosine kinase, and aurora kinase A have shown promise in various malignancies by inhibiting cell cycle progression and suppressing the growth of 3D tumor spheroids." (PMID 41226237, 2025). "Overall, these findings reveal a tumor-suppressive role of METTL1-mediated tRNA m7G modification in breast cancer, selectively promoting translation of GADD45A and RB1 to induce G2/M cell cycle arrest, suggesting a potential strategy to improve CDK4/6 inhibitor therapy." (PMID 41562049, 2025). "These include the cyclin-dependent kinase 4/6 (CDK4/6) inhibitor trilaciclib that induces a transient and reversible arrest of hematopoietic stem and progenitor cells, thereby protecting them from the neutropenic impacts of chemotherapeutic agents that remain effective against the tumor cells." (PMID 40002910, 2025). "Evidence that CDK4/6 inhibitors reduce angiogenesis is model-dependent, but suppression of E2F-dependent pro-angiogenic programs, including VEGF, has been reported in some studies and may contribute to decreased tumor vascularization." (PMID 41280894, 2025). "Key gaps include a lack of predictive biomarkers, limited understanding of ER isoform expression patterns and unknowns about how CDK4/6 inhibition affects the tumour microenvironment in non-breast contexts." (PMID 40563591, 2025). "In addition, CDK4/6 inhibitors can enhance glycolysis and oxidative metabolism while depleting reducing agents NADPH and glutathione, thereby increasing the apoptosis rate of tumor cells." (PMID 41259313, 2025). "Using an immune-competent model of de novo MPNSTs, developed through the Cas9-mediated inactivation of Nf1 and Cdkn2a, we found that the combination of CDK4/6 and MEK inhibitors uniquely induced transient tumor regression, a phenotype not seen in immune-deficient preclinical models." (PMID 40723291, 2025). "Meanwhile, it was revealed that both free PROTAC and preparations inhibited proliferation only at high PROTAC concentrations in mouse fibroblast L-929 and human umbilical vein endothelial (HUVEC) cells, due to different expression levels of CDK4/6 in tumor cells and nontumor cells." (PMID 39419977, 2024). "Despite the diagnostic implications that the overlap of genetic alterations in neoplasms with changes in genes within the 12q13-15 region could create, the discovery of coamplifications of MDM2 with CDK4 and GLI1 offers new therapeutic targets in neoplasms with MDM2/CDK4 amplification." (PMID 38275873, 2024). "In recurrent tumors, genotype cluster 3 environments, with high frequencies of both EGFR-only amplified and EGFR/CDK4 co-amplified cells, lose their connection with hypoxic (phenotype cluster 4) and tumor-cell-rich nonvascularized immunodepleted environments (phenotype cluster 5)." (PMID 38805346, 2024). "This suggests the potential use of MDM2 or CDK4 inhibitors in neoplasms where alterations in these genes do not aid the pathological diagnosis but may help identify potential therapeutic targets." (PMID 38275873, 2024).